KLF13 (KLF transcription factor 13)
Diseases named in the same sentence as KLF13 in open-access papers (continued):
Sharing a sentence is not in itself a finding about the gene and the disease.
tumor (continued). "Clearly, we do not know enough about the specifics of KLF9 and KLF13 actions in the tumor immune cell microenvironment, a deficiency that should be rectified." (PMID 38067370, 2023). "Additionally, the knockdown of HMG-CoA synthase repressed cholesterol biosynthesis and the proliferation of silenced KLF13 tumor cells in CRC." (PMID 38023258, 2023). "Tumor xenograft model also confirmed the tumor suppressor role of KLF13 on tumor growth of THCA." (PMID 37817224, 2023). "These outcomes further determined the tumor suppressor effect of KLF13 on THCA." (PMID 37817224, 2023). "In this article, we summarize the work that has identified the roles of KLF9 (and to a lesser degree KLF13) in tumor suppression or promotion via unique effects on differentiation, pro- and anti-inflammatory pathways, oxidative stress, and tumor immune cell infiltration." (PMID 38067370, 2023). "KLF13 expression in tumor tissues was significantly lower than that in normal tissues." (PMID 36336731, 2022). "Besides, results of IHC assay also indicated that KLF13 obviously inhibited Ki67 expression, along with down-regulating the protein expressions of β-catenin and its downstream Cyclin D1 and c-Myc in tumor tissues." (PMID 36336731, 2022). "Furthermore, KLF13 overexpression resulted in cell cycle arrest at G0/G1 phase, reduced EdU incorporation and suppressed tumor growth of HCT116 cells in nude mice." (PMID 32523679, 2020). "Our study revealed KLF13 as a tumor suppressor in CRC by regulating cholesterol metabolism." (PMID 32523679, 2020). "However in prostate cancer, KLF13 functions as a tumor suppressor by inactivating AKT signaling pathway." (PMID 32523679, 2020). "Xenografter tumor growth was used to evaluate the in vivo effect of KLF13 in CRC." (PMID 32523679, 2020). "KLF13 may be a tumor suppressor or promoter is depending on the tissue." (PMID 40450000, 2025). "Experiments using an EC xenograft model demonstrated that the oncogenic role of KLF13 was mediated through regulation of GPIHBP1, as tumor size, tumor volume and tumor weight were all greatly reduced in KLF13 + shGPIHBP1 group relative to those in KLF13 group." (PMID 40450000, 2025). "To elucidate the possible mechanism responsible for the low expression of KLF13 in NSCLC cells, we focused on CAFs, a major constituent in the tumour microenvironment." (PMID 41410190, 2025). "IHC staining of tumor tissues showed that KLF13 and GPIHBP1 expression were increased in KLF13 overexpressing mice, while they were decreased in mice with GPIHBP1 knocked down." (PMID 40450000, 2025). "Compared to para-tumor specimens, the mRNA levels of KLF5, KLF7, KLF8, and KLF13 were elevated, whereas those of KLF4, KLF6, and KLF10 were reduced in HCC specimens." (PMID 37554278, 2023). "Some of the ways to get at this question include Chip-Seq, single cell RNA-seq, and single cell proteomics studies for multiple normal and tumor cell types and tissues simultaneously for both KLF9 and KLF13." (PMID 38067370, 2023). "Such a tumor inductive scenario (if confirmed) can be approached in two ways, i.e., targeting the suppressors of KLF9 and KLF13 and targeting KLF16." (PMID 38067370, 2023). "Consistent with this, tumor cell levels of KLF9 and KLF13 are positive factors for overall survival of patients with clear cell renal cancer." (PMID 38067370, 2023). "Of interest, by binding to UNR, clofoctol activates the transcription factor Kruppel-like factor 13 (KLF13), known as a tumor suppressor gene and as a regulator of T cell differentiation." (PMID 35587469, 2022). "In addition, upregulation of p‐AKT in Exos‐treated tumours was reversed by BKM120, whereas downregulation of KLF13 and upregulation of miR‐3126‐5p, SH2B1, IRS1, and p‐PI3K caused by Exos were not affected by BKM120 co‐administration." (PMID 41410190, 2025). "Upregulated KLF13 levels were found in tumor tissues relative to those in adjacent non-cancerous specimens." (PMID 40450000, 2025).
tumor (continued). "FBW7 (F-box and WD Repeat Domain-containing 7), a component of the ubiquitylation pathway(s), is a tumor suppressor for multiple human cancers and a negative regulator of steady-state levels of KLF13." (PMID 38067370, 2023). "The extent of KLF9 and KLF13 co-expression and co-functionality in tumor cells, as well as in the non-malignant cells residing within the tumor microenvironment, is another key question to be addressed." (PMID 38067370, 2023). "Strategies focused on regulating essential genes, such as KLF13 and SREBP1/SREBP2, can suppress cell proliferation and tumor growth but may only universally apply to some molecular subtypes of CRC." (PMID 38023258, 2023). "It is therefore tempting to speculate that the down regulation of KLF9 and/or KLF13 in pre-neoplastic cells leads, in turn, to synergistic inductions in KLF16 expression and consequent tumor promotion." (PMID 38067370, 2023). "Lastly, it is possible that KLF13 impacts tumoral CCL5 expression, with the latter molecule having major effects on immune cell infiltration into multiple tumor types, and with predicted positive as well as negative effects on tumor immune response." (PMID 38067370, 2023). "The roles (similar or different) of KLF9 and KLF13 in cancer stem cells and whether reductions or absence of KLF expression drives tumor cell metastasis also requires follow up." (PMID 38067370, 2023).
cancer (14 papers, 2017 to 2025). A tumor composed of atypical neoplastic, often pleomorphic cells that invade other tissues. "The known associations of KLF9 and KLF13 with cancers in humans (and relevant mouse models) are summarized below." (PMID 38067370, 2023). "It binds to GC-rich sequences and associated GT and CACCC boxes.The function of KLF13 on cancer progression are diverse in different cancers." (PMID 37817224, 2023). "Lastly, with respect to the future drugging of KLF9 and KLF13 for possible applications in cancer therapies, one goal would be to identify small molecule inducers of these mRNAs/proteins in pre-neoplastic and malignant cells." (PMID 38067370, 2023). "The increased interest that KLF9 and KLF13 have received in the oncology world portends an even more exciting future for these proteins in cancer prevention and treatment." (PMID 38067370, 2023). "The present review, in contrast, concentrates on the paralogous KLF9 and KLF13, their known roles in the suppression or promotion of cancer development, and the current gaps in knowledge regarding their respective biology, signaling, and oncogenic mechanisms." (PMID 38067370, 2023). "Another pathway that integrally utilizes KLF9 and KLF13, and which has potential implications in oncogenesis and cancer therapy, is the circadian clock." (PMID 38067370, 2023). "Elucidation of KLF9 and KLF13 in cancer biology is likely to provide new inroads to the understanding of oncogenesis and its prevention and treatments." (PMID 38067370, 2023). "An examination of a current DNA methylation database (MethHC 2.0) indicates that KLF9 and KLF13 gene promoter regions are over- or under-methylated in small subsets of human cancers." (PMID 38067370, 2023). "Here, we describe the salient features of KLF9 and KLF13, the current state-of-the-art research regarding both protein’s actions in cancer development and response to therapies, and where the field requires further exploration." (PMID 38067370, 2023). "KLF9 (and to a lesser degree KLF13) represses the cancer stem cell phenotype in glioblastoma and ovarian cancer, and thus, perhaps other cancers as well." (PMID 38067370, 2023). "Although some research data, including ours and others, suggest that KLF13 suppresses cell proliferation in some cancer types, the effects of KLF13 on cancer initiation and progression are still poorly understood." (PMID 36336731, 2022). "Studies concerning the involvements of KLF13 in different cancer processes such as metastasis, differentiation, inflammation, angiogenesis, chemoresistance, immune response, are few." (PMID 36336731, 2022). "Western blot analysis indicated that KLF13 expression was strong in normal gastric epithelial cell line GES-1 while it was quite weak in two cancer cell lines BGC-823 and SGC-7901." (PMID 36336731, 2022). "As a suppressive transcription factor, KLF13 has been found to be involved in some cell processes of several cancer types." (PMID 36336731, 2022). "Additionally, in non-cancer cells, miR-125a-5p also has a role in suppressing classical activation of macrophages while promoting alternative activation by targeting Kruppel-like transcription factor 13 (KLF13), which negatively regulates inflammation associated with T cell activation." (PMID 28580184, 2017). "KLF13 function even varies among different cell types in the same cancer." (PMID 40450000, 2025). "Kruppel-Like Factor 13 (KLF13) has strong effects on cancer occurrence and progression." (PMID 40450000, 2025). "KLF13 knockdown counteracted the anti‐cancer action of exosomal miR‐3126‐5p inhibition." (PMID 41410190, 2025). "The results indicated that multiple genes and transcriptional factors related to cancer apoptosis and progression, such as Bak1, Bcl-2, KLF13 and STAT3, might be the target genes of miR-125b." (PMID 28176874, 2017). "We identified several TFs, including GTF2I, NFIB, NFATC4, ZNF37A, KLF13, and ZNF507, involved in cancer metastasis." (PMID 39273015, 2024).
cancer (continued). "However, the cases where TF and TPAC scores do have a consistent direction of association for a cancer type across all of the Hallmark gene sets, e.g, KLF13, THAP11 and IRF7 for GBM, are consistent with prior findings on TFs whose activity is linked to cancer (KLF13, THAP11, and IRF7)." (PMID 38206988, 2024). "One important physiological context for cancer pre-disposition in which KLF9 and KLF13 are known to intersect in function is adipogenesis." (PMID 38067370, 2023). "Known and predicted targets of miR-125b reported in prior studies of cancers characterized by BRAF alterations include MLK3, KLF13, CXCL11, and FOXA1." (PMID 30131528, 2018). "KLF13 has significant effects on growth and other physiological processes in human cancers; however, there are no reports to date of functional effects of KLF13 in EC." (PMID 40450000, 2025). "In the cases of KLF9 and KLF13, this discordance has not been thoroughly examined for numerous cell or tissue types (including cancers), but this possibility should be considered when assigning function based solely on assays of mRNA abundance." (PMID 38067370, 2023). "Since cholesterol biogenesis may promote the growth of cancer cells, we knocked down HMGCS1 in KLF13 knockdown CRC cells." (PMID 32523679, 2020). "It seems reasonable that such complexes, along with changes in KLF phosphorylation and acetylation status (more for KLF13 than KLF9), will underpin the convergence of signaling pathways as well as growth and nutrient signals at the level of KLF target genes in pre-cancerous and cancer cells." (PMID 38067370, 2023). "To date, this information is absent for KLF9 and KLF13 in most human cancers." (PMID 38067370, 2023). "The earliest study in this area described the effect of KLF13, but not KLF9, on increasing the apoptosis of PANC1 cancer cells in vitro." (PMID 38067370, 2023).
psychiatric disorder (2 papers, 2021 to 2024). A disorder characterized by behavioral and/or psychological abnormalities, often accompanied by physical symptoms. "This study aims to highlight the potential involvement of the KLF13 gene in neurodevelopmental and psychiatric disorders." (PMID 39202416, 2024). "The 15q13.3 microdeletion syndrome is a genetic disorder characterized by a wide spectrum of psychiatric disorders that is caused by the deletion of a region containing 7 genes on chromosome 15 (MTMR10, FAN1, TRPM1, MIR211, KLF13, OTUD7A, and CHRNA7)." (PMID 33785025, 2021).
heart disease (1 paper, 2015). "For example, KLF13 is an important component of the transcription network required for heart development and suggests that KLF13 be a GATA-4 modifier, by analogy to other GATA-4 collaborators, mutations in KLF13 may be causative for congenital human heart disease." (PMID 26085920, 2015).
kidney diseases (1 paper, 2024). "Our previous work found that KLF13 and its pharmacological agonist, Clo, inhibit TGF‐β activity and prevent fibrosis in kidney diseases." (PMID 38973459, 2024).
KLF13 also shares sentences with these, for which no sentence is quoted: adenocarcinoma (1 paper); Ataxia (1); Atrophy (1); autism spectrum disorder (1); AV block (1); blood cancers (1); breast carcinoma (1); cardiomyopathy (1); clear cell renal cell carcinoma (1); diabetic cardiomyopathy (1); endometrial cancer (1); epilepsy (1); genetic disorder (1); glioblastoma (1); hypertrophic cardiomyopathy (1); Intellectual disability (1); intraepithelial cervical neoplasia (1); invasive breast carcinoma (1); lung squamous cell carcinoma (1); Myocardial fibrosis (1); neurodevelopmental disorder (1); non-alcoholic fatty liver disease (1); non-small cell lung carcinoma (1); Patent ductus arteriosus (1); polycystic ovary syndrome (1); psoriasis (1); pulmonary fibrosis (1); schwannoma (1); Sinus bradycardia (1); Skeletal muscle atrophy (1).
A further 2 diseases each share a sentence with KLF13 in 1 paper.